LEPR (leptin receptor)
Diseases named in the same sentence as LEPR in open-access papers (continued):
Sharing a sentence is not in itself a finding about the gene and the disease.
lymphoma (1 paper, 2022). A malignant (clonal) proliferation of B- lymphocytes or T- lymphocytes which involves the lymph nodes, bone marrow and/or extranodal sites. "Those notions are especially significant since NF-kB, STAT3, PI3K, and AKT pathways are activated in lymphoma cells via leptin/LEPR signaling and improving bcl-2 expression." (PMID 36555171, 2022). "Similar to leptin genes, the relationship between the concentration of circulating leptin or LEPR expression and lymphomas has also been studied." (PMID 36555171, 2022).
lymphopenia (1 paper, 2012). Reduction in the number of lymphocytes. "Since leptin is required for lymphopoiesis, leptin receptor-deficient mice have fewer circulating B- and CD4+ T-lymphocytes and are unable to correct irradiation-induced lymphopenia." (PMID 22313574, 2012).
myocardial ischemia (1 paper, 2012). A disorder of cardiac function caused by insufficient blood flow to the muscle tissue of the heart. "The upregulation of IL-6 and the increase in its signaling product hs-CRP suggests the possible involvement of leptin in the signaling cascade through activation of leptin receptor after myocardial ischemia." (PMID 22891684, 2012).
non-alcoholic steatohepatitis (1 paper, 2021). "For instance, non-alcoholic steatohepatitis (NASH) or cirrhosis in general, may alter the process of trace mineral metabolism, and decreased Zn level was associated with hepatic steatosis with a leptin receptor deficiency or dysregulation of a large number of genes in lipid metabolism." (PMID 34771023, 2021).
non-Hodgkin lymphoma (1 paper, 2022). Distinct from Hodgkin lymphoma both morphologically and biologically, non-Hodgkin lymphoma (NHL) is characterized by the absence of Reed-Sternberg cells, can occur at any age, and usually presents as a localized or generalized lymphadenopathy associated with fever and weight loss. "LEPR gene polymorphisms are closely related to the risk of non-Hodgkin’s lymphoma." (PMID 36147491, 2022).
oral cancers (1 paper, 2014). "In conclusion, our findings suggest a need for further investigation of the relationship between variants of the LEPR gene and the development and progression of oral cancer." (PMID 26034683, 2014). "Other studies are needed to understand the role of LEPR variants in the development and progression of oral cancers, especially in relation to Leptin levels or in association with the stages of dysplasia." (PMID 26034683, 2014). "It has been suggested that there is an association between Leptin receptor Gln223Arg polymorphisms and increased risk for oral cancer." (PMID 26034683, 2014). "We found only one published study that investigated the LEPR Gln223Arg polymorphism in oral cancer." (PMID 26034683, 2014). "Therefore, in order to obtain better knowledge about the Leptin receptor gene in oral cancer, we evaluated polymorphic variants of LEPR Gln223Arg in the mucosa of patients with OSCC and PMOL compared to normal oral mucosa." (PMID 26034683, 2014).
Polydipsia (1 paper, 2022). Excessive thirst manifested by excessive fluid intake. "The diabetic db/db mice present a spontaneous mutation of the leptin receptor also show polydipsia as well as increased food intake." (PMID 35990356, 2022).
prostate adenocarcinoma (1 paper, 2019). "This suggestion is reinforced by the fact that the expression of LEP, leptin receptor (LEPR) and its main downstream signaling genes (JAK2, STAT3) is reduced in prostate adenocarcinoma, suggesting that this system is involved in the mechanism of apoptosis defense in proliferating tumor cells." (PMID 31671654, 2019).
renal fibrosis (1 paper, 2023). A final common manifestation of a wide variety of chronic kidney diseases characterized by glomerulosclerosis and tubulointerstitial fibrosis. "To investigate whether FXR is involved in the process of renal fibrosis in DN, and to observe the effects of FXR knockout on renal fibrosis in db/db mice, we bred FXR & leptin receptor double knockout mice." (PMID 37790634, 2023).
sarcopenia (1 paper, 2011). Progressive decline in muscle mass due to aging which results in decreased functional capacity of muscles. "Further, leptin receptor numbers may be reduced along with muscle mass in patients with sarcopenia, possibly resulting in further increases in plasma leptin concentration." (PMID 21931785, 2011).
spina bifida (1 paper, 2020). A congenital neural tube defect in which vertebrae are not fully formed. "Variants in the lipid metabolism genes APOB and LEPR appear to contribute to lumbar sacral spina bifida in the present study." (PMID 32650820, 2020). "A study in Ireland of 520 spina bifida cases and their families and 994 controls found over-transmission of the LEPR rs1805134 minor C allele associated with spina bifida (relative risk of 1.5 fold)." (PMID 32650820, 2020).
spina bifida aperta (1 paper, 2020). "In eleven cases affected by thoracic lumbar spina bifida aperta there were 3 PDRVs in the lipid metabolism genes LEPR and APOB (P = 0.029)." (PMID 32650820, 2020). "Similar to our results, LEPR rs1137100 G allele showed a significant increase in the risk of an NTD-affected offspring when inherited from the mother (2.43 fold), and an increased risk for lower spina bifida aperta (Lumbar 1 and lower, 3.20 fold)." (PMID 32650820, 2020).
systemic sclerosis (1 paper, 2019). A chronic disorder, possibly autoimmune, marked by excessive production of collagen which results in hardening and thickening of body tissues. "Moreover, an elevated serum level of leptin receptor could be a clinically useful marker of systemic sclerosis spectrum diseases (SSDs) and its measurement over time in patients with SSD may lead to early detection of SSc." (PMID 30806766, 2019).
thymus atrophy (1 paper, 2021). Acquired diminution of the size of the thymus associated with wasting as from death and reabsorbtion of cells, diminished cellular proliferation, decreased cellular volume, pressure, ischemia, malnutrition, reduced function or malfunction, or hormonal changes. "Experimentally, mice with leptin deficiency or leptin receptor deficiency have been shown to have thymus atrophy and poor immune response." (PMID 33907162, 2021).
thyroiditis (1 paper, 2022). Inflammation of the thyroid gland. "After administration of Allo-aca, an antagonist of the leptin receptor, thyroiditis in EAT mice was significantly alleviated, manifested as reduced thyroid follicle destruction, decreased lymphocyte infiltration, and decreased serum thyroid autoantibody levels." (PMID 36339447, 2022).
tongue cancer (1 paper, 2021). A malignant neoplasm affecting the tongue. "Previous studies have reported that the expression of LEPR 42, PFKM 43, 44, PGK1 45, 46, CYP19A1 47, 48, SLC20A1 49, and ZC3H12D 50 were associated with tumorigenesis and progression in various tumor types, which support the further identification and exploring in tongue cancer." (PMID 33758601, 2021). "PGK1, SLC20A1, LEPR, CYP19A1, ZC3H12D, and PFKM were found to be independent predictors in tongue cancer." (PMID 33758601, 2021).
tongue tumor (1 paper, 2021). "In our study, we did find the abnormally upregulation of LEPR, PFKM and PGK1 in tongue tumor patients and their upregulation are related to patients' poor overall survivals." (PMID 33758601, 2021).
Truncal obesity (1 paper, 2017). Obesity located preferentially in the trunk of the body as opposed to the extremities. "We also observed an increased leptin receptor levels in CRF-OE mice which may be related to possible leptin resistance due to truncal obesity, as shown by the correlation between leptin receptor expression and circulating leptin levels." (PMID 28101317, 2017).
vitiligo (1 paper, 2023). Generalized well circumscribed patches of leukoderma that are generally distributed over symmetric body locations and is due to autoimmune destruction of melanocytes. "It is worth noting that the mRNA expression level of LEPR was significantly up-regulated in vitiligo skin lesions (P = 0.013), while LEP wasn’t." (PMID 37207234, 2023). "The expression of LEPR in patients with vitiligo is correlated with the expression of cytotoxic cytokines by CD8+ T cells to some extent." (PMID 37207234, 2023). "Flow cytometry showed that the LEPR expression in CD8+ T cells of PBMCs from patients with vitiligo was higher than that in healthy controls." (PMID 37207234, 2023). "LEPR probably promoted the secretion of cytotoxic cytokines from CD8+ T cells in patients with vitiligo." (PMID 37207234, 2023). "RT-qPCR (p = 0.013) and immunofluorescence staining (p = 0.0053) verified that LEPR expressed significantly higher in vitiligo." (PMID 37207234, 2023). "We also found that serum leptin was decreased while the expression of LEPR was increased in patients with vitiligo." (PMID 37207234, 2023). "Notably, the expression of LEPR in the skin tissues of patients with vitiligo was significantly higher than that of healthy controls." (PMID 37207234, 2023). "We proposed a hypothesis that Leptin positively regulates the expression of LEPR in vitiligo, and patients with vitiligo have higher uptake and utilization of leptin than healthy controls." (PMID 37207234, 2023). "LEP or LEPR may become a new target for the treatment of vitiligo." (PMID 37207234, 2023). "Enrichment analysis verified that lipid metabolism is likely to be closely related to the pathogenesis and disease progression of vitiligo, especially the PPAR signaling pathway, of which LEP and LEPR are representative genes." (PMID 37207234, 2023).
tumor (127 papers, 2006 to 2026). "In summary, the acquisition of an oncogenic RAS mutation sparks the perfect crosstalk between tumour-initiating cells and their microenvironment, enabling them to hijack the LEPR-signalling pathway and fuel cancer progression." (PMID 36450983, 2022). "By contrast, rapamycin had less effect on Leprnull tumours, the growth of which was already restricted by LEPR loss of function." (PMID 36450983, 2022). "We demonstrated that GLS loss in tumor endothelium leads to decreased leptin but increased leptin receptor levels in E0771 tumors." (PMID 36381236, 2022). "In human cell lines and animals, LEPR was reported to be associated with increased tumour cell proliferation, metastasis, angiogenesis and drug resistance." (PMID 33397392, 2021). "Among White women, only increasing BMI was associated with higher LEPR IHC expression, and higher LEPR IHC expression was associated with larger tumor size, positive lymph node status, and ER− status." (PMID 32046756, 2020). "Similar to the observations reported herein, there is evidence that lower LEPR IHC is associated with clinicopathologic features indicative of tumor progression or aggressiveness in other obesity-related cancers." (PMID 32046756, 2020). "Similar to leptin, the association of leptin receptor expression across the grades of the tumor was statistically significant with p value being 0.018, as assessed via Fisher’s exact test." (PMID 30803210, 2019). "Breast tumor expression of leptin receptor in conjunction with elevated circulating leptin is associated with poor prognosis and tumor metastasis." (PMID 27338371, 2016). "Recently, three single nucleotide polymorphisms in the leptin receptor gene (K109R, K656N and Q223R) were identified to be associated with increased BC risk, suggesting that tumor leptin receptor signaling can directly influence tumor growth and progression." (PMID 25360510, 2014). "Leptin receptor expression was associated with older age, greater tumor size, extrathyroidal extension, lymph node metastasis, and advanced tumor stage, so in summary aggressive behavior of PTC and poor disease survival were observed." (PMID 24049662, 2013). "Conversely, db/db mice, which express leptin but have a mutation in the leptin receptor, displayed small tumors, suggesting that leptin has a tumor-suppressive role." (PMID 22853690, 2012). "High levels of serum Ob-R are also associated with smaller tumor sizes, which suggests that leptin receptor shedding may occur in small tumors and larger tumors maintain higher leptin receptor expression." (PMID 37626804, 2023). "Moreover, there was a positive association between advanced tumor stages and leptin/leptin receptor plasma levels." (PMID 37942199, 2023). "Reduced LEPR levels were suggested to be associated with more aggressive tumours." (PMID 35328822, 2022). "It seems that the downregulation of LEPR expression in RCC tumours may be related to the methylation in the promoter-associated CpG sites of LEPR." (PMID 35328822, 2022). "Additionally, leptin and leptin receptor-deficient animal models presented resistance to induced tumor development, corroborating the important role of leptin in tumorigenesis." (PMID 33371214, 2020). "Leptin and leptin receptor are found in epithelial cancer cells and they are linked to tumour growth, cell death impairments and angiogenesis induction via increased FGF-2 and VEGF expression, moreover leptin has been shown to be related to chemotherapy responsiveness." (PMID 33371214, 2020). "In addition, high expression levels of tumor-associated leptin receptor are thought to promote tumor growth and progression." (PMID 28160559, 2017). "The association between leptin receptor and adiponectin receptor expression with tumor stage suggests that adipocytokines may influence tumor biology." (PMID 23304125, 2012).
tumor (continued). "In vitro, leptin stimulation increases cellular migration, and in vivo, in murine models, depletion of the leptin receptor reduced orthotopic tumor growth in obese mice." (PMID 40940878, 2025). "LEP stimulates tumor cell proliferation, inhibits cell apoptosis and promotes angiogenesis by binding to its receptor LEPR." (PMID 38694509, 2024). "Mice were used to determine the effectiveness of the gamma-secretase inhibitor (DAPT, Notch inhibitor), the interleukin-1 receptor antagonist (Anakinra) and the leptin receptor antagonist (Allo aca) against tumor growth." (PMID 38152619, 2023). "Methylation of the leptin receptor gene is lower in tumor samples than in adjacent non-tumor samples and its mRNA levels are directly related to the appearance of metastatic cells." (PMID 36674935, 2023). "In this direction, tumor progression inhibition has been induced by targeting the leptin receptor (Ob-R) in BALB/c mice bearing C26 colon carcinoma after Doxil administration." (PMID 37760840, 2023). "Present study showed that LEPR was expressed in 70.5% of tumor tissues, which was significantly higher than 56.3% of benign breast tissues and 44.0% of normal para-carcinoma tissues." (PMID 36941557, 2023). "In the present study, tumor formation was significantly promoted in the db/db mice, which showed leptin receptor dysfunction and elevated serum leptin levels, suggesting that using db/db mice is the most important point in our model." (PMID 37834032, 2023). "Among them, CXC-motif chemokine receptor 4 (CXCR4) 34, leptin receptor (LEPR) 35, and Hepatitis A virus cellular receptor (HAVCR1) 36 are linked to tumor progression." (PMID 37056934, 2023). "How alterations in LEPR signalling contribute to tumour progression and metastasis has remained unclear." (PMID 36450983, 2022). "The decrease of leptin and increase of leptin receptor in GLSECKO tumors was further confirmed by quantitative RT-PCR analyses on isolated tumor cells." (PMID 36381236, 2022). "Many articles show a significant relationship between LEPR expression level and tumour aggressiveness, invasion, metastasis and clinical outcome in RCC." (PMID 35328822, 2022). "Recent work has identified specific cell types other than adipocytes that harbor leptin and leptin receptor expression, particularly in cancers and tumor microenvironments, and characterized the role of this signaling axis in cancer progression." (PMID 33799880, 2021). "Regarding the leptin receptor, the IHC score was also significantly higher in animals with a luminal B tumor subtype than in healthy animals (2.50 vs. 1.75; p = 0.0425)." (PMID 33644151, 2021). "In a study of squamous cell carcinoma of the skin, leptin receptor expression as evaluated by immunostaining was significantly correlated with poor differentiation, proliferation index and tumor histologic grade." (PMID 33799880, 2021). "A clear common up-activation pattern is observed in tumor samples of three cancer types, but only LEPR and CCNA2 nodes are differentially expressed in the same direction in all three cancers." (PMID 34039407, 2021). "Cancer cells release leptin and express leptin receptor (LEPR), which suggests that leptin/LEPR signalling plays roles in tumour progression." (PMID 33397392, 2021). "For example, a peptide-based leptin receptor antagonist showed to decrease tumor burden in mice bearing orthotopic xenograft breast tumors." (PMID 33535537, 2021). "There is a correlation between the SNPs of the LEPR and the likelihood of a tumor occurring in humans." (PMID 33369452, 2020). "We would also measure FGFR1, LepR, and phospho-Jak2 protein expression in tumor tissue since one shortcoming of our study is that many of our correlations involve mRNA." (PMID 33019728, 2020). "While positive signal for leptin receptor was present in every Leydig cell of control tissue, it was present occasionally in cells of the tumor." (PMID 32455738, 2020).